NFE4 (nuclear factor, erythroid 4)
Description:
Functions as part of the SSP (stage selector protein) complex, a complex that contributes to the preferential expression of the gamma-gene in fetal erythroid cells by facilitating the interaction of the gamma-globin genes with enhancer elements contained in the locus control region (LCR). The complex binds to the stage selector element (SSE) in the proximal gamma-globin promoter. In contrast, isoform 2 acts as a repressor of gamma-globin gene expression by preventing NFE2 and RNA polymerase II recruitment to the promoter.
Synonyms: NF-E4
Gene: Long non-coding RNA gene on chromosome 7 (102,973,354 to 102,988,856, forward strand). Ensembl gene ENSG00000230257.
Subcellular location: Nucleus
Diseases named in the same sentence as NFE4 in open-access papers:
NFE4 is named in the same sentence as 5 diseases in open-access papers, as found by Europe PMC text mining. Sharing a sentence is not in itself a finding about the gene and the disease. The quoted sentences say what the papers report.
clear cell renal cell carcinoma (2 papers, 2023 to 2024). "Moreover, the preferential expression of the gamma-globin genes was regulated by NFE4, which was an indispensable component in the prognostic model of clear-cell renal-cell carcinoma." (PMID 36737692, 2023).
renal carcinoma (2 papers, 2023 to 2024). A carcinoma arising from the epithelium of the renal parenchyma or the renal pelvis. "LINC02154, AC112715.1, AC092535.5, and AC105105.3 were all significantly upregulated in three renal cancer cell lines, while the expression of IGFL2-AS1 and NFE4 was elevated in some renal cancer cell lines." (PMID 37893009, 2023). "The expression of IGFL2-AS1 was only increased in the renal carcinoma cell line 769-P, while the expression of NFE4 was increased in the renal carcinoma cell lines ACHN and CAKI-1." (PMID 37893009, 2023).
carcinoma (1 paper, 2024). A malignant tumor arising from epithelial cells. "Given that only LINC02154 and NFE4 expression was upregulated in ccRCC and that LINC02154 has been described as a cuproptosis-linked gene and well-studied in various carcinomas including ccRCC, NFE4 was primarily focused." (PMID 38797784, 2024).
tumor (1 paper, 2024). "We performed functional expression assessment for four m6A-associated lncRNAs, which showed that NFE4 and LINC02154 expression was upregulated in tumor tissues and they served as the risk factors in the high-risk cohort because of their overexpression in subcohort." (PMID 38797784, 2024).
NFE4 also shares sentences with these, for which no sentence is quoted: tendinitis (1 paper).